MYD88 (MYD88 innate immune signal transduction adaptor)
Diseases named in the same sentence as MYD88 in open-access papers (continued):
Sharing a sentence is not in itself a finding about the gene and the disease.
liver fibrosis (continued). "Inhibition of the key factors on the axis MyD88/TLR-CXCL2-CXCR2-NLRP3 may provide potential prevention and treatment strategies for liver fibrosis." (PMID 34830293, 2021). "Furthermore, MyD88 in macrophages enhanced CXCL2 secretion and activated NLRP3 inflammasome in HSCs, which in turn promoted liver fibrosis." (PMID 34830293, 2021). "Furthermore, dioscin was effective in suppressing the TLR4/MyD88/NF-κB signaling pathway to inhibit HSCs activation and reduce ECM accumulation for attenuating liver fibrosis in vivo and in vitro." (PMID 26655640, 2015). "The current study showed that Cx3cr1+Ccr2+ Mo-macs expressed the adaptor Myd88 and activated the transcription of S100A4 via CX3CR1/MyD88/NF-κB signaling pathway, resulting in the activation of HSCs and thereby promoting the progression of inflammation and liver fibrosis." (PMID 38627387, 2024). "However, the specific role of MyD88 in myeloid cells in liver fibrosis has not been thoroughly investigated." (PMID 34830293, 2021). "To date, the specific function of MyD88 in macrophages in liver fibrosis has not been reported." (PMID 34830293, 2021). "Similarly, MyD88−/−, but not TRIF−/−, mice demonstrated reduced fibrogenic gene expression at the early phase after BDL, whereas both MyD88−/− and TRIF−/− mice had reduced liver fibrosis at the late phase of liver fibrosis." (PMID 20706677, 2010).
asthma (46 papers, 2010 to 2025). "The top 20 genes including the PTBP1, RAB11FIP3, APH1A, and MYD88 were recognized as the most frequent items among severe asthma association rules." (PMID 37717070, 2023). "Nonetheless, the mechanism underlying TLR4/MyD88/NF-κB activation in asthma remains to be further explored." (PMID 35156897, 2022). "The reduced expression of MyD88 after treatment with pro-/pre-biotics implicated their role in preventing eosinophilic infiltration in asthma." (PMID 35296330, 2022). "In summary, we determined that lncRNA-AK149641 participated in the asthma-associated inflammatory response via the NF-κB signaling pathway probably by regulating expressions of p-NF-κB p65 and MyD88." (PMID 32929606, 2020). "Despite the results obtained in TLR4-deficient mice or deficient in downstream molecules indicating that TLR4 signaling is required to induce airway hypersensitivity, some studies showed that experimental asthma is easily induced in TLR4-deficient or MyD88-deficient mice." (PMID 29867994, 2018). "The ACAA1 SNP that modified the association between endotoxin and asthma risk is found less than 10 kb from MYD88, in a region that may regulate MYD88 transcription." (PMID 22151743, 2011). "This signaling is particularly relevant in viral-induced asthma, highlighting the critical role of MyD88-dependent pathways in linking microbial exposure to immune dysregulation in allergic diseases." (PMID 40672946, 2025). "Second, many other pathways, such as PI3K/Akt/mTOR pathway, TLR4/MyD88/NF-κB pathway, and Wnt/β-catenin pathway, are involved in the regulation of airway inflammation and remodeling in asthma." (PMID 38168709, 2024). "MUC1-CT reduces NLRP3 inflammasome-mediated pyroptosis by inhibiting the activation of the TLR4/MyD88/NF-κB pathway, thereby attenuating neutrophil airway inflammation in patients with asthma." (PMID 37880668, 2023). "This study explored the inhibitory effect of MUC1 on NLRP3 inflammasome-mediated pyroptosis in patients with asthma and revealed that one of the underlying mechanisms is the downregulation of TLR4/MyD88/NF-κB pathway activation." (PMID 37880668, 2023). "Studies have revealed that TLR4/MyD88/NF-κB pathway suppression can attenuate pathological mechanisms of asthma." (PMID 37880668, 2023). "This study aimed to explore the influence of MUC1 on neutrophil airway inflammation in patients with asthma and verify the underlying mechanism associated with the TLR4/MyD88/NF-κB pathway and NLRP3 inflammasome-mediated pyroptosis." (PMID 37880668, 2023). "Mechanistic studies revealed that MUC1 reduced NLRP3 inflammasome-mediated pyroptosis by inhibiting TLR4/MyD88/NF-κB pathway activation, thereby suppressing neutrophilic airway inflammation in patients with asthma." (PMID 37880668, 2023). "In the mice models of asthma, MyD88 expression was found to be a critical factor for eosinophilic inflammation in ECs." (PMID 35296330, 2022). "We found that DCs expressing MyD88 molecule were necessary and sufficient for CpG-induced attenuation of established asthma." (PMID 32391011, 2020). "In experimental asthma, MyD88 expression in epithelial cells mediates eosinophilia whereas MyD88 expression in conventional dendritic cells controls the neutrophilic response." (PMID 32321514, 2020). "A key molecule in TLRs signaling is MyD88 and as such MyD88 has gained great of interest as an important adaptor molecule in development of asthma." (PMID 29867994, 2018). "The importance of MyD88 in induction of experimental asthma was further proved when Alternaria extract is co-administered with OVA." (PMID 29867994, 2018). "IL-33 plays an important role in driving mast cell responses and promoting type-2 allergic inflammation, particularly with respect to asthma, via MyD88-integrated crosstalk amongst the IL-33 receptor (ST2), TLR4 and FcεRI." (PMID 29540770, 2018).
asthma (continued). "We have previously shown in the OVA-model of asthma that eLPS administration during alum-based allergen sensitization blocked the development of lung TH2 immune responses via MyD88 pathway and IL-12/IFN-γ axis." (PMID 23805294, 2013). "The physiological relevance of these findings is further suggested by the major acceleration of OVA-induced asthma in MyD88 invalidated mice." (PMID 20628601, 2010). "Similarly, studies have demonstrated that inhibition of TLR4/MyD88/NF-κB signaling can attenuate asthma and protect airways against allergic responses and inflammation." (PMID 39364406, 2024). "Moreover, inhibition of PI3K/Akt/mTOR and TLR4/MyD88/NF-κB signaling with targeted molecules can attenuate pathological mechanisms of asthma and play an important role in protecting airways against allergic response and inflammation pathology." (PMID 35444643, 2022). "Furthermore, the inhibition of TLR4/MyD88 signaling by the PEP-NASP peptide in our HDM-induced asthma model significantly decreased mucin hyperexpression and airway inflammation." (PMID 36012669, 2022). "Our results suggest that this type of immunotherapy might be of potential use to treat eosinophilic (type 2 high) asthma endotype and indicate the pivotal role of dendritic cell expressing Myd88 in this process." (PMID 32391011, 2020). "Thus, our data indicates that the therapeutic effect of liposomal formulation in established asthma requires CpG signaling through MyD88 molecule expressed on CD11c-positive putative DCs." (PMID 32391011, 2020). "It has remained elusive whether the toll-like receptors (TLR2)/mycloid differentiation factor 88 (MyD88)/nuclear factor (NF)-κB signaling pathway is involved in lipoxin A4 (LXA4)-induced protection against asthma." (PMID 25760938, 2015). "The MYD88 dependent signaling cascade ultimately results in the production of IL-12, a cytokine responsible for differentiation of Th1 cells that down-regulate the asthma-promoting Th2 response." (PMID 22151743, 2011). "Interestingly, previous studies had shown the anti-inflammatory function of MUC1 in asthma, by reducing the NLRP3 inflammasome-mediated pyroptosis through the inhibition of the TLR4/MyD88/NF-κB pathway, thereby suppressing neutrophilic airway inflammation in patients with asthma." (PMID 41295249, 2025). "However, whether MUC1 regulates NLRP3 inflammasome-mediated pyroptosis through the TLR4/MyD88/NF-κB pathway in asthma remains unknown." (PMID 37880668, 2023). "Importantly, the TLR4/MyD88/NF-κB axis is reported to partake in asthma’s pathogenesis." (PMID 35156897, 2022). "Stimulation of the MyD88/NF-κB pathway enhances the production of proinflammatory cytokines, whereas the TRIF pathway contributes to asthma exacerbation." (PMID 40672946, 2025). "The relationship between asthma and the TLR4/NF-κB/MyD88 signaling pathway is complex and diverse, involving the regulation of multiple immune responses and inflammatory responses." (PMID 38672467, 2024). "In asthma, HMGB1 expression induces HSP expression through the TLR4 / MYD88 / NF-kB pathway, which eventually produces IL-4 and IL-13." (PMID 37422662, 2023). "Several studies have shown that many molecular signaling pathways, such as JAK/STAT/MAPK, NF-κB, Wnt/β-catenin, PI3K/Akt, JNK, Fas/FasL, TLRs/MyD88, and Keap1/Nrf2/ARE, are important in the pathophysiology of asthma." (PMID 34446024, 2021). "Our study suggests a mechanism by which evodiamine hinders the development of asthma in rats by altering expression of TLR-4, NF-κB, MyD88, and HMGB1, thus hindering airway remodelling in the rat lung." (PMID 33577738, 2021). "Lower levels of TLR-4, MyD88, NF-κB, and HMGB1 mRNA in lung tissue were measured in the evodiamine-treated group than in the asthma group." (PMID 33577738, 2021). "In a model of ovalbumin-induced asthma, treatment with BML-111 reduces NF-κB activation and the upstream adaptor molecule myeloid differentiation primary response 88 (MyD88) in the lungs and recruited immune cells." (PMID 32604968, 2020).
asthma (continued). "In addition, the protein expression levels of NLRP3, caspase-1, cleaved caspase-1, GSDMD, GSDMD-N, IL-18, and IL-1β were increased, indicating that MUC1, TLR4/MyD88/NF-κB pathway, and NLRP3-induced pyroptosis are involved in the pathogenesis of asthma." (PMID 37880668, 2023). "Furthermore, this study adds to the evidence that MUC1 regulates the TLR4/MyD88/NF-κB pathway and NLRP3 inflammasome-mediated pyroptosis in patients with asthma." (PMID 37880668, 2023). "In the cellular and mouse model of asthma, lipopolysaccharide (LPS) could combine with toll-like receptor 4 (TLR4) to activate myeloid differentiation primary response 88 (MyD88), and the nuclear transposition of NF-κB happened then." (PMID 36582191, 2022). "In the progression of asthma, lung IMs may be tightly related to TLR4/MyD88 pathway to produce IL-10 for anti-inflammation and to regulate Th2- and Th17-mediated inflammation." (PMID 36582191, 2022). "Thus, as both LPS/TLR4 and IL-33/ST2 signal via MyD88, there is potential for crosstalk between TLR4 and IL-33R (ST2) on mast cells to promote pathogenesis and exacerbation of asthma." (PMID 29540770, 2018). "We have previously shown that TLR4 agonist (LPS) adsorbed to OVA/alum prevented the development of asthma-like responses via MyD88, but not TRIF pathway." (PMID 26380316, 2015). "The mRNA expressions of TLR4, MyD88, nucleotide-binding oligomerization domain-like pyrin domain-containing protein 3 (NLRP3), caspase-1, interleukin (IL)-18, and IL-1β in induced sputum cells of patients with asthma were upregulated and related to the mRNA expression of MUC1." (PMID 37880668, 2023). "As observed in vitro, Myd88, NF-κB, and p38 may be involved in EMT in the mouse model of asthma." (PMID 32793232, 2020). "Indeed, in HDM-mediated asthma models, TLR4 expression by airway epithelial cells has been shown to contribute in a MyD88-dependent but TRIF-independent fashion to the development of an IL1-, alarmin-, and GM-CSF-mediated DC activation to allow the development of a pathogenic Th2 response." (PMID 29201030, 2017). "The involvement of TLR2, TLR4 and MyD88 in the pathogenesis of AAD and asthma is incompletely understood, and has not been studied in S. pneumoniae-mediated suppression of AAD." (PMID 27309732, 2016). "Interestingly, in some models, MyD88 molecule appears to be more relevant than TLR4 since MyD88 expression, but not TLR4, was critical for induction of experimental asthma induced by Alternaria extract." (PMID 29867994, 2018).
autoimmune disease (45 papers, 2011 to 2026). A disorder resulting from loss of function or tissue destruction of an organ or multiple organs, arising from humoral or cellular immune responses of the individual to their own tissue constituents. "Mutation of PTPN6 has been linked with autoinflammatory and autoimmune diseases, and phosphorylation of MyD88 is a prerequisite for the induction of inflammatory disease in PTPN6-mutated mice." (PMID 32365080, 2020). "Apart from hyperactivation of myeloid cells including the increased expression of BAFF, a well-known factor associated with abnormal B cell responses and autoimmune diseases, we demonstrate here that MyD88−/− mice develop hyperactivation of Th2 and Tfh cells." (PMID 29973931, 2018). "MyD88-deficient mice are for the most part resistant to autoimmune disease, and are unable to reject minor- and major-mismatched allograft transplants." (PMID 28611775, 2017). "Several modulatory factors in the TLR signaling pathway including IRF3, IRF7, IRF8, TRIM20, MYD88 and NF-κB1 have been associated with autoimmune disease." (PMID 26794091, 2016). "MyD88-dependent intracellular signalling cascades and subsequently NF-kappaB-mediated transcription lead to the dynamic inflammatory processes underlying the pathogenesis of rheumatoid arthritis (RA) and related autoimmune diseases." (PMID 35002734, 2021). "Although MyD88 is crucial for a host to prevent pathogenic infection, misregulation of its abundance might lead to autoimmune diseases." (PMID 32365080, 2020). "Numerous studies have indicated that MYD88 activation plays a vital role in driving autoimmunity and promoting autoimmune disease progression." (PMID 36457997, 2022). "IRF3 and IRF7, which are associated with MyD88-independent pathway of TLR4 signalling, also play crucial roles in development of autoimmune disease or CRSwNP, and these molecules are thought to act as pro-inflammatory transcription factors in these diseases." (PMID 35256715, 2022). "Huang and Yang confirmed the role of the TLR9/MyD88 pathway in the regulation of adaptive immune responses in autoimmune diseases." (PMID 36405992, 2022). "IL1RL1 activates the MyD88/NF-κB signaling pathway to promote the suppressive effect of Tregs in inflammatory diseases, but the role of IL-33 in autoimmune diseases and tumors is controversial." (PMID 34012433, 2021). "Recently, new studies have focused on the involvement of several proteins in the TLR7 signaling pathways (e.g., TLR7 and MyD88), which have been identified as potential therapeutic targets for the treatment of autoimmune diseases." (PMID 33767707, 2021). "MyD88 has a clear relationship with infectious diseases, tumors, and autoimmune diseases; and an MyD88-dependent pathway is considered as a vital target for intervention treatment of these diseases." (PMID 32848639, 2020). "The pathological role of MyD88-dependent innate immune signaling in autoimmune diseases including AS has been studied using mouse models, such as NOD mice." (PMID 30250175, 2018). "Given its role in determining T-cell phenotype, targeted inhibition of MyD88-mediated signaling represents an appealing therapeutic strategy for organ transplantation and autoimmune disease." (PMID 28611775, 2017). "Given its central role in signal-transduction pathways that promote inflammatory Th1 development, MyD88 is an attractive target for therapeutic interventions in autoinflammatory and autoimmune diseases." (PMID 28611775, 2017). "Inhibition of mutated MyD88 mediated signaling, on the other hand, can prevent replication of cancer cells, therefore inhibition of MyD88 signaling may be important for cancer, autoimmune disease and response to infection." (PMID 35069570, 2021). "Given the importance of DAMPs in the activation of Myd88-dependent pathways in other autoimmune diseases, we performed studies to evaluate ECM expression and anti-ECM antibodies in the context of pSS using the well-established pSS mouse model, NOD.B10-H2b (NOD.B10)." (PMID 34381449, 2021).
autoimmune disease (continued). "As a canonical adaptor for the Toll-like receptor (TLR) family, myeloid differentiation primary response protein 88 (MyD88) has crucial roles in host defense against infection by microbial pathogens, and its dysregulation might induce autoimmune diseases." (PMID 32365080, 2020). "To study whether TLR signaling is important for the development of Btk-mediated autoimmune disease, we crossed CD19-hBtk mice onto a MyD88-deficient background and aged these mice to characterize their phenotype." (PMID 30761150, 2019). "Mice lacking MyD88 are highly susceptible to infectious diseases, but tend to resist experimentally induced autoimmune diseases such as experimental autoimmune encephalomyelitis (EAE) and manifest diminished allograft rejection." (PMID 28611775, 2017). "Although these results point to an important role for TLR7 and 9 in SLE development, it is important to note that mice deficient in TLR7/9 as well as MyD88 are not free of autoimmune disease symptoms." (PMID 23936008, 2013). "The dysregulation of MyD88 may also induce autoimmune diseases." (PMID 36032091, 2022). "Because the MyD88-Syk axis activates rapidly in macrophages during inflammatory responses, selective targeting of one or both of these molecules may be a promising strategy to prevent and treat inflammatory and autoimmune diseases." (PMID 35003083, 2021). "Misregulation of MyD88 signaling results in excessive inflammation and the production of proinflammatory cytokines and interferons that are detrimental to health and might lead to pathological damage, such as cancer and autoimmune diseases." (PMID 32365080, 2020). "Hence, the roles of TLR- and MyD88-dependent signaling are indeed complex in a variety of systems and operate differently in specific cell types, emphasizing the need for ongoing dissection of this important aspect of autoimmune disease." (PMID 28278279, 2017). "While the significance of B cell-intrinsic Myd88-dependent TLR signaling in pSS is poorly understood, the importance of these pathways in other autoimmune diseases is evident." (PMID 34381449, 2021). "We demonstrated that TLR signaling is important in hBtk-mediated autoimmune disease, although the in vitro BCR responsiveness of CD19-hBtk B cells, including downstream signaling, survival and proliferation, was enhanced in a MyD88-independent fashion." (PMID 30761150, 2019). "Autoimmune disease in MRL-lpr mice is dependent on TLR7, TLR9, and toll-like receptor (TLR) signal transduction molecule Myeloid differentiation primary response 88 (MYD88)." (PMID 31824490, 2019). "Other models of autoimmune disease, such as traditional induction of autoimmune encephalomyelitis by administration of MOG35–55 peptide, have been shown to be dependent on MyD88 gene function as well." (PMID 25229618, 2014). "Moreover, the differential expression of HLA family molecules, particularly in relation to MYD88 and CD36, aligns with previous findings on the role of HLA genes in immune response and autoimmune diseases." (PMID 38919626, 2024). "Activation of Myd88 is central to many autoimmune diseases, as mice lacking Myd88 have attenuated pathology." (PMID 34381449, 2021). "In the absence of MyD88, mice are mostly resistant to the induction of autoimmune diseases such as collagen induced arthritis and EAE14,61." (PMID 29930295, 2018). "Mice lacking either the combined TLR7/9 or MYD88 do not develop autoimmune disease." (PMID 31824490, 2019).